PEBP1 (phosphatidylethanolamine binding protein 1)
Diseases named in the same sentence as PEBP1 in open-access papers (continued):
Sharing a sentence is not in itself a finding about the gene and the disease.
bacterial infections (1 paper, 2022). "Drosophila PEBPs are associated with fitness through their role in innate immunity, which is evidenced by the upregulation of PEBP genes during infections and the protection against bacterial infections conferred by the overexpression of PEBP1." (PMID 35396341, 2022).
PEBP1 also shares sentences with these, for which no sentence is quoted: colorectal cancer (30 papers); metastatic tumors (15); cervical cancer (11); lymph node metastasis (9); breast tumor (8); nasopharyngeal carcinoma (8); non-small cell lung carcinoma (8); acute myeloid leukemia (7); multiple myeloma (7); esophageal cancer (6); heart failure (6); pancreatic adenocarcinoma (6); adenocarcinoma (5); gastrointestinal stromal tumor (5); systemic inflammatory response syndrome (5); endometrial cancer (4); esophageal squamous cell carcinoma (4); lung squamous cell carcinoma (4); Obesity (4); triple-negative breast carcinoma (4); gastric cardia adenocarcinoma (3); ischemic stroke (3); lymphoma (3); nervous system diseases (3); non-Hodgkin lymphoma (3); prostate (3); stomach cancer (3); Stroke (3); B-cell lymphoma (2); cardiac diseases (2).
A further 98 diseases each share a sentence with PEBP1 in 2 papers or fewer.